METTL3 (methyltransferase 3, N6-adenosine-methyltransferase complex catalytic subunit)
Diseases named in the same sentence as METTL3 in open-access papers (continued):
Sharing a sentence is not in itself a finding about the gene and the disease.
lung cancer (continued). "Compared with normal tissues, higher expression of METTL3 was found in human lung cancer and colon adenocarcinoma tissues." (PMID 33816306, 2021). "In this study, we found that METTL3 is up-regulated in lung cancer, and overexpressed METTL3 mediates m6A modification of LCAT, leading to its stabilization, thus providing molecular insight for LCAT3 overexpression in LUAD." (PMID 34274028, 2021). "In lung cancer tissues, METTL3 can trigger the splicing of the precursor miR-143-3p to generate mature miR-143-3p, which targets three binding sites in the vasohibin (VASH) 1 promoter and inhibits its expression." (PMID 34858499, 2021). "METTL3 has been shown to be involved in the dissemination and metastasis of lung cancer cells by mediating the epithelial-mesenchymal transition (EMT) by a mechanism dependent on its m6A catalytic activity." (PMID 34638933, 2021). "The results showed that high METTL3 expression levels in lung cancer were significantly correlated with poor patient prognosis." (PMID 33495421, 2021). "With that, METTL3 accelerates the translation of oncogene by promoting ribosome recycling, thereby providing an easier way for the invasion and metastasis of lung cancer cells." (PMID 34957092, 2021). "In lung cancer cells, knocking out METTL3 can increase the apoptosis of tumor cells to suppress the tumorigenicity of cancer cells." (PMID 34858499, 2021). "METTL3 has been shown to promote the expression of some crucial oncoproteins and facilitate tumour proliferation, apoptosis, and invasion in human lung cancer." (PMID 35004679, 2021). "METTL3 contributes to TGF-β induced epithelial-mesenchymal transition through the regulation of JUNB in lung cancer." (PMID 34277630, 2021). "We propose that this phenotypic difference likely reflects the target specificity of METTL3-mediated m6A modified RNAs in different types of lung cancer cells, as well as tremendous genetic or epigenetic heterogeneity." (PMID 33676554, 2021). "The interaction between METTL3 and eIF3h is essential for translation and oncogenic transformation in lung cancer." (PMID 34568001, 2021). "In lung cancer, METTL3 expression, as well as m6A RNA modification, was remarkedly increased in TGF-β-induced epithelial−mesenchymal transition of lung cancer cells." (PMID 34001850, 2021). "M6A methyltransferase METTL3 activates the splicing of precursor miR-143-3p to promote lung cancer brain metastasis through VASH1 regulation." (PMID 34150845, 2021). "METTL3 has been shown to facilitate miR-143-3p biogenesis, promoting the brain metastasis in lung cancer patient samples through the miR-143-3p/Vasohibin/VEGFA axis." (PMID 34616742, 2021). "In a previous study of brain metastasis of lung cancer, METTL3 was found to intensify the splicing of miR-143-3p therefore elevating its biogenesis in raising the cell motility." (PMID 33882457, 2021). "We thus knocked out METTL3 using the CRISPR/Cas9 system in lung cancer cells, and the knockout efficiency was confirmed by both western bolt and dot blot." (PMID 34274028, 2021). "For instance, the direct combination of METTL3 and ribosomes promoted the interaction between METTL3 and translation initiation, thereby enhancing the translation of mRNA and promoting tumor progression of lung cancer." (PMID 33879256, 2021). "In lung cancer, METTL3 enhanced circularization and translation of m6A modified mRNAs, and thus promoted oncogenesis." (PMID 34149801, 2021). "For example, in lung cancer, patients with high expression of METTL3 were prone to occur lymph node metastasis and distant metastasis." (PMID 32513173, 2020). "Specially, METTL3 induces the methylation of N6-adenosine and can facilitate oncogenic translation by binding to the initiation machinery of translation in human lung cancer." (PMID 33048840, 2020). "Loss- and gain-of-function studies have further confirmed that METTL3 promotes the proliferation and invasion of lung cancer cells." (PMID 33228740, 2020).
lung cancer (continued). "In human lung cancer, METTL3 acts as a translation promoter for mRNAs of epidermal growth factor and Hippo pathway effector TAZ by recruiting the eukaryotic initiation factor 3 (eIF3)." (PMID 32194861, 2020). "Two recent studies from the same group revealed intriguing effects of METTL3 in lung cancer progression." (PMID 32404927, 2020). "METTL3 has been found to promote protein translation of oncogenes in lung cancer cells through methyltransferase-independent activity." (PMID 32903217, 2020). "METTL3 also accelerates the maturation of miR-143-3p, leading to the formation of METTL3/miR-143-3p/vasohibin-1 axis to favor the metastasis of lung cancers." (PMID 32767982, 2020). "The m6A methyltransferase METTL3 is upregulated in lung cancer and is required for the growth, survival, and invasion of cancer cells." (PMID 31131257, 2019). "METTL3 was upregulated in primary human lung adenocarcinomas compared with adjacent normal tissues, and METTL3 depletion suppressed the growth of lung cancer xenografts in vivo." (PMID 31921660, 2019). "METTL3 acts as a oncogene in lung cancer by increasing EGFR and TAZ expression and promoting cell growth, survival and invasion." (PMID 31142332, 2019). "An interaction between molecules like microRNAs and m6A alterations was also depicted, with miR-33a inhibiting lung cancer cells proliferation by targeting METTL3." (PMID 30428628, 2018). "In human lung cancer cells, METTL3 promotes the translation of specific genes, such as EGFR (epidermal growth factor receptor) and Hippo pathway effector, TAZ (tafazzin), through recruitment of eIF3 to the translation initiation complex." (PMID 29439529, 2018). "METTL3 is significantly upregulated in lung cancer, in turn, promoting cellular proliferation, survival, and metastasis." (PMID 29439529, 2018). "Here, our research presents a novel mechanism of Cr (VI) carcinogenicity, and METTL3 may be a potential therapeutic target for lung cancer." (PMID 41362669, 2026). "We then carried out Kaplan–Meier survival analysis to explore the correlation of METTL3 overexpression with the prognosis of human lung cancer patients by analyzing cohorts of four independent Gene Expression Omnibus (GEO) datasets (GSE17710, GSE30219, GSE4573, and GSE19188)." (PMID 41362669, 2026). "In lung cancer, the m6A writer METTL3 has been most widely and intensively studied." (PMID 39967906, 2025). "reviewed the critical role and potential mechanisms of METTL3 in the progression of lung cancers." (PMID 40717692, 2025). "Interestingly, Tgfβ1 has also been reported to positively regulate Mettl3 expression in lung cancer cells, thereby inducing EMT." (PMID 41360769, 2025). "Beyond inflammatory and fibrotic disorders, we also summarize emerging evidence linking METTL3 to lung cancer and briefly outline other respiratory conditions (e.g., ILD, bronchiectasis, and secondary pulmonary hypertension), highlighting common translational themes and remaining gaps." (PMID 41515964, 2025). "METTL3 was also found to be upregulated in lung cancer in previous studies." (PMID 39095708, 2024). "For instance, miRNA-600 suppresses lung cancer progression via targeting METTL3." (PMID 38075202, 2024). "The reduction in METTL3 expression mediated by miR‐338‐5p disrupts nuclear oncogene c‐Myc‐mediated m6A modifications, leading to decreased expression of c‐Myc and consequent suppression of the proliferation, invasion, and migration of lung cancer cells." (PMID 38706740, 2024). "However, the precise molecular mechanism through which METTL3 promotes metastasis in lung cancer remains incompletely understood, and further investigation is warranted to explore the downstream molecular pathways it regulates." (PMID 38238831, 2024). "By preliminary screening of existing literature, we narrowed the list down to 28 candidate genes relevant to lung cancer that might be methylation targets of METTL3." (PMID 39095708, 2024).
lung cancer (continued). "We subsequently investigated whether METTL3 exerts regulatory effects on candidate signatures, given its role as a key m6A writer in lung cancer." (PMID 39720723, 2024). "In addition, in lung cancer, β-elemene targets and inhibits METTL3 expression at both RNA and protein levels." (PMID 37996892, 2023). "We believe that SOX2OT acting as ceRNA to protect mRNA of METTL3/14/IGF2BP2 and guiding METTL3/14/IGF2BP2 to GLI1 mRNA is the pivotal mode of action of SOX2OT in GLI1 regulation since SOX2OT is located mainly in the cytoplasm of lung cancer cells (>85% in A549 and >70% in H1299 cells)." (PMID 37149646, 2023). "In lung cancer, it has been shown that METTL3 can boost progenitor miR-143-3p splicing to support its biosynthesis and that m6A may stimulate progenitor miR-143-3p splicing to facilitate the production of mature miRNAs." (PMID 38125749, 2023). "Notably, when METTL3 was knocked down in lung cancer cells, the stimulating effect of CAFs on tumor growth was significantly diminished." (PMID 37056933, 2023). "Moreover, miR-600 can attenuate METTL3 expression and restrain the migration and proliferation of lung cancer cells." (PMID 36614216, 2023). "Interestingly, when METTL3 was knocked down in lung cancer cells, the increase in m6A modification by CAFs was attenuated." (PMID 37056933, 2023). "The expression levels of METTL3 in lung cancer cells were detected by qPCR and western blotting." (PMID 37056933, 2023). "Similar to this, METTL3 may boost miR-143-3p splicing in lung cancer (LC) cells to create more mature miRNAs and encourage lung cancer brain metastasis." (PMID 38125749, 2023). "Consequently, we knocked down METTL3 by siRNA transfection in lung cancer cells and then analyzed the expression levels of FTH in H1299 and A549 cell lines." (PMID 37259333, 2023). "For example, METTL3 was found essential for TGF-β-induced epithelial-mesenchymal transition of lung cancer cells; YTHDF2 could promote lung cancer cell growth via facilitating 6PGD mRNA translation." (PMID 34996469, 2022). "Similarly, METTL3 also regulated miR-143-3p/VASH1 axis to enhance the angiogenesis ability of lung cancer cells in an m6A manner." (PMID 35331234, 2022). "Thus, METTL3 participates in the initiation and development of lung cancer by modifying noncoding RNA." (PMID 35331234, 2022). "In addition, several groups supported findings showing that downregulation of METTL3 expression levels through miR-600, miR-33a or RNAi clearly inhibited the oncogenic activities of lung cancer cells." (PMID 36446846, 2022). "In the present review, we will discuss the underlying molecular mechanism of METTL3 in the occurrence and development of lung cancer and predict the future research direction, as well as the potential clinical application of targeting METTL3 in lung cancer treatment." (PMID 35331234, 2022). "Notably, there is solid evidence that METTL3 can act as an oncogene in lung cancer cell lines but as a tumor suppressor in tumor stromal cells." (PMID 35331234, 2022). "For example, knockdown of Nutm2a-as1 can regulate Mettl3 to inhibit lung cancer progression." (PMID 35692827, 2022). "Interestingly, miR-186 and miR-600 appear to similarly target METTL3 and inhibit the progression of hepatoblastoma and lung cancer." (PMID 35794625, 2022). "METTL3 has been identified to be a therapeutic target for lung cancer." (PMID 36008805, 2022). "The depletion of METTL3 suppressed translation and oncogenesis of lung cancer." (PMID 36536402, 2022). "For example, METTL3 could promote lung cancer tumor growth and invasion by boosting the translation of EGFR or TAZ transcripts independent of its catalytic activity." (PMID 36008805, 2022). "Accumulating evidence has shown that abnormal m6A levels mediated by METTL3 are involved in the malignant progression of lung cancer, including cell proliferation, invasion, metastasis, angiogenesis, drug resistance, glycolysis, cancer stem cells, and tumor environment." (PMID 35331234, 2022).
lung cancer (continued). "METTL3 could also promote translation of certain oncogenic mRNAs, and METTL3 depletion could sensitize lung cancer cells to BRD4 inhibition and inhibit tumorigenicity." (PMID 36058919, 2022). "Therefore, the regulatory network with METTL3 as the core in lung cancer is extremely complex and involves many molecular mechanisms." (PMID 35331234, 2022). "Recent research reveals that METTL3 is upregulated in lung cancer." (PMID 36008805, 2022). "Interestingly, METTL3 can stimulate the translation of a set of oncogenes independently of m6A modification in lung cancer." (PMID 34722298, 2021). "As previous research showed that in bladder cancer METTL3/YTHDF2 m6A axis accelerates carcinogenesis by degrading transcription factor KLF4, we also examined whether METTL3/YTHDF2 m6A axis inhibited KLF4 expression in lung cancer." (PMID 34774019, 2021). "Finally, we treated lung cancer cells with actinomycin D to block transcription and found that METTL3 knockdown significantly decreased the half-life of LCTA3 transcript." (PMID 34274028, 2021). "Interestingly, METTL3 was initially identified as a cytoplasmic m6A reader in lung cancer and it was shown to promote translation of a subset of modified mRNAs by promoting mRNA circularization." (PMID 34561421, 2021). "In addition, another study has shown that METTL3 can improve the expression of c-Myc by increasing m6A modification, whereas miR-338-5p inhibit the expression of METTL3 to interfere with the lung cancer progression." (PMID 35004679, 2021). "MiR-600 inhibited the progression of lung cancer through reducing METTL3 expression." (PMID 34150845, 2021). "METTL3 was observed to be overexpressed in human lung cancer tissues compared with normal tissues." (PMID 34638933, 2021). "Additionally, m6A methylase METTL3 was found to accelerate translation of oncogenes in lung cancer and consequently enhancing the growth, survival, and invasion of cancer cells." (PMID 33882457, 2021). "Additionally, the precursor of miR-143-3p has been reported as a direct target of METTL3 in promoting brain metastasis of lung cancer." (PMID 34638933, 2021). "In addition, miR-186 and miR-600 have also been reported to target METTL3 and suppress hepatoblastoma and lung cancer progression, respectively." (PMID 34315512, 2021). "Cytological experiments have demonstrated that METTL3 affects the growth, survival, and invasion of human lung cancer cells, which implies that METTL3 plays an important role in the long-term effects on pulmonary vasculature function following postnatal exposure to hypoxia." (PMID 33902609, 2021). "Moreover, METTL3 can regulate the expression of several important proteins that regulate the survival, apoptosis, invasion, and proliferation of lung cancer cells." (PMID 34395520, 2021). "Meanwhile, the level of m6A decreased in lung cancer cells that METTL3 was knocked down, suggesting that METTL3 may affect the expression of MET through the m6A pathway." (PMID 33491264, 2021). "A similar functioning mode was found in lung cancer cells demonstrating that METTL3 could recruit translation initiation factors (for example eIF3h) to augment the translation of oncogenes (for example TAZ), independent of its catalytic activity." (PMID 34895230, 2021). "The METTL3–eIF3h interaction is hence a potential therapeutic target for lung cancer patients." (PMID 34638933, 2021). "In addition, in NSCLC, miR-600 induced the mitochondrial apoptosis signaling pathway by downregulating METTL3 expression to promote apoptosis and inhibit proliferation and invasion of lung cancer cells." (PMID 34108450, 2021). "Moreover, miR-33a inhibited the migration and proliferation of lung cancer cells by directly targeting the 3′-UTR of METTL3 and decreasing its mRNA levels." (PMID 34108450, 2021).
lung cancer (continued). "One major question that remains is whether m6A regulators participate in the development of tumors in a manner dependent on m6A, just as METTL3 promotes lung cancer in an independent manner of its catalytic activity." (PMID 34381710, 2021). "In addition to promoting tumorigenesis by the m6A writer mechanism, METTL3 was also shown to promote lung cancer while acting as an m6A reader." (PMID 34638933, 2021). "Likewise, an m6A methyltransferase, methyltransferase‐like 3 (METTL3) has been reported to promote transforming growth factor‐β‐dependent EMT in lung cancer by regulating the transcription factor JUNB." (PMID 33931980, 2021). "Prior studies have validated that METTL3 is overexpressed in lung cancer." (PMID 33643384, 2021). "We found KLF4 expression were enhanced following METTL3 or YTHDF2 knockdown in lung cancer cells." (PMID 34774019, 2021). "In summary, the results show that METTL3 promotes the occurrence and development of tumors by enhancing the synthesis of tumor-promoting factor miRNAs in bladder, colorectal, pancreatic, and lung cancers." (PMID 34108450, 2021). "Moreover, in lung cancer METTL3 localized to the cytoplasm, where it can act as m6A reader and promotes translation of m6A modified mRNAs." (PMID 34561421, 2021). "METTL3 expression correlated with brain metastasis and worse prognosis in lung cancer." (PMID 33926554, 2021). "In NSCLC, the expression level of METTL3 was higher in lung cancer than in normal tissues." (PMID 34108450, 2021). "Moreover, knockdown of METTL3 also inhibited the growth of lung cancer by inducing apoptosis via PI3K/AKT pathway." (PMID 32201509, 2020). "MiR-33a can decrease the expression of Mettl3 in lung cancer cells to suppress cell proliferation." (PMID 32444598, 2020). "Additionally, METTL3 plays an important role in TGF-β-induced EMT in lung cancer, mainly by promoting the m6A modification, increasing the total mRNA level, and enhancing the mRNA stability of JUNB, one of the most important transcriptional regulators of EMT." (PMID 32398132, 2020). "METTL3 acts as an oncogene in lung cancer via different mechanisms." (PMID 32513173, 2020). "METTL3 is also downregulated by miR-600, which induces the apoptosis of lung cancer." (PMID 32767982, 2020). "miRNA‐600 reverses METTL3‐induced tumorigenesis and progression of lung cancer." (PMID 33029866, 2020). "Also, METTL3 facilitates the biogenesis of miR-143-3p to promote the brain metastasis of lung cancer via regulation of VASH1." (PMID 32513173, 2020). "It indicates that METTL3 conveys oncogenic signals to potentiate aggressiveness in lung cancer." (PMID 33029866, 2020). "However, the results from an American research team indicated that METTL3 can increase the invasiveness of lung cancer cells by initiating the translation of oncogenes (EGFR, TAZ, and MAPKAPK2)." (PMID 32175271, 2020). "Besides, the Bax/Bcl-2 ratio in lung cancer cells was increased by the transfection of miRNA of METTL3, which suggested that apoptosis was inhibited in cancer cells." (PMID 32201509, 2020). "The m6A writer METTL3 has also been reported to promote lung cancer survival, growth, and invasion." (PMID 32195181, 2020). "METTL3 promotes the proliferation, survival, migration, and invasion of human lung cancer cells." (PMID 31921660, 2019). "Collectively, these studies on METTL3 in lung cancer suggest the oncogenic role of METTL3." (PMID 31921660, 2019). "By doing so, METTL3 promoted growth, survival, and invasion in lung cancer cells." (PMID 29374143, 2018). "Elevated METTL3 palys an oncogenic role in lung cancer, while METTL3 is downregulated in NSCLC." (PMID 30062093, 2018). "The roles of METTL3 in lung cancer are inconsistent across different studies." (PMID 30062093, 2018). "Similarly, oncogenic function of m6A demethylase FTO and Methyltransferase Like 3 (METTL3) has been revealed in acute myeloid leukemia and lung cancer, respectively." (PMID 30212448, 2018).